IL10 (interleukin 10)
Diseases named in the same sentence as IL10 in open-access papers (continued):
Sharing a sentence is not in itself a finding about the gene and the disease.
ischemia (continued). "In animal model of acute lung inflammation induced by intestinal ischemia/reperfusion or LPS, LLLT has relieved airway inflammation through the induction of IL-10 and reduction of TNF and macrophage inflammatory protein-2 (MIP-2) expression." (PMID 24319484, 2013). "In order to determine if IL-10 affects developmental angiogenesis in the retina, we utilized the oxygen-induced retinopathy (OIR) model to induce tissue ischemia and compensatory retinal neovascularization." (PMID 18852882, 2008). "Among the modulatory molecules that could be involved in the post-ischemia outcome of HFD mice are IL4 and IL10." (PMID 39624169, 2024). "Activated microglia serve a dual role during ischemia, releasing pro-inflammatory cytokines (such as TNF-α and IL-1β) that can aggravate ischemic injury, whilst promoting the release of anti-inflammatory cytokines (such as IL-10) to reduce ischemic injury." (PMID 36725745, 2023). "Based on this information, we studied pro-inflammatory (IL-6, TNF-alpha, and IL-1beta) and anti-inflammatory (IL-10 and TGF-beta) cytokines with ELISA to clarify whether there were any corresponding changes between them during different stages of ischemia." (PMID 37822799, 2023). "On day 35, intramuscular transplantation of hiPSC-MSCs in the MSC-Saline group did not significantly improved IL-10 relative to ischemia group." (PMID 36008710, 2022). "Stimulated by platelet-derived growth factor, adipose tissue-derived mesenchymal stem cells (ASCs) can release EVs that are rich in anti-inflammatory and immunoregulatory factors and induce an increase in the production of IL-10 and TGF-β1, thereby protecting muscles against acute ischemia." (PMID 35052570, 2021). "Pyruvate is a key intermediate in energy metabolism, but the renal cortical pyruvate has been depleted in mice subjected to ischemia or glycerol-induced AKI; pyruvate administration confers a marked protection against AKI by increasing anti-inflammatory IL-10 and HO-1 levels." (PMID 31072024, 2019). "Moreover, the administration of a LXA4 analog was found to induce IL-10 secretion and to prevent the tissue damage, TNF-α secretion and lethality of mice subjected to intestinal ischemia/reperfusion." (PMID 25853847, 2015). "Despite this, the study is limited to the time points examined and does not rule out a possible late role of IL-10 after 3 days post-ischemia involving other brain cells." (PMID 24499655, 2013). "Collectively, these findings indicate that, within the studied range, neither the choice of cardioplegic solution nor the duration of ischemia had a statistically significant impact on the myocardial release of IL-4, IL-6, IL-10, leptin, TNF-α following ischemia/reperfusion injury." (PMID 40729334, 2025). "It is not entirely clear how metformin stimulates IL-10 production in ischemia-affected brains." (PMID 33915857, 2021). "We analysed YB‐1‐mediated expression of the immune regulatory cytokine IL‐10 in both LPS and sterile inflammation induced by unilateral renal ischaemia–reperfusion (I/R) and found an important role of YB‐1 not only in the onset but also in the resolution of inflammation in kidneys." (PMID 28664613, 2017).
Cirrhosis (62 papers, 2013 to 2026). A chronic disorder of the liver in which liver tissue becomes scarred and is partially replaced by regenerative nodules and fibrotic tissue resulting in loss of liver function. "A study explored the impact of genetic polymorphisms (IL-18, IFN-c, and IL-10) on the risk of cirrhosis in chronic hepatitis C patients." (PMID 40165825, 2025). "Elevated IL-10 levels have been associated with disease progression from the inactive carrier state to cirrhosis and eventually to HCC in HBV-infected individuals." (PMID 41462970, 2025). "Increased IL-10 production in the setting of cirrhosis can inhibit efficient immune responses and raise the risk of bacterial infections." (PMID 38894778, 2024). "IL-10 RS180096 TT genotype, IL-10-592 CA polymorphism, and IL-10 ACC haplotype are good markers for HCV patients to develop cirrhosis and HCC susceptibility." (PMID 36117587, 2022). "Cytokines such TNF-α, IL-10 and IL-17A are well described in association with chronic hepatitis, cirrhosis and HCC in combination with other proinflammation cytokines." (PMID 33435966, 2021). "In our study, the amelioration of cirrhosis-associated immune dysfunction by propranolol treatment was accompanied by a decrease in the frequency of Treg cells and corresponding TGFβ1, IL-10 and IL-35 levels in circulation and in the spleen." (PMID 32138352, 2020). "With this objective, we have assessed the influence of TNF-α and IL-10 single nucleotide polymorphisms on the progression of HCV-induced chronic hepatitis to cirrhosis in HIV-coinfected patients." (PMID 23840511, 2013). "To investigate the cellular immune status in cirrhosis, we studied T cell responses in vitro and their association with markers of bacterial translocation, serum IL-10, monocyte HLA-DR expression and T cell subsets in cirrhotic patients without SIRS." (PMID 23446058, 2013). "IL-10 polymorphism has already been found to increase the risk of developing cirrhosis." (PMID 39596809, 2024). "Therefore, we explored the effect of the pro‐inflammatory properties of IL‐2‐330 (rs2069762), IL‐8 (rs2227306), TNF‐α−857 (rs1799724), and TNF‐α−1031 (rs1799964) versus the anti‐inflammatory properties of IL‐10‐1082 (rs1800896), IL‐10‐592 (rs1800872) on the risk of cirrhosis." (PMID 39315805, 2024). "Our study demonstrated that rs1800896 AA and rs1799964 TT showed an interaction on reducing the risk of cirrhosis and a similar effect with rs1800896 AA and rs1799724 CT/TT genotype, suggesting IL‐10 and TNF‐α may have a synergistic effect in LC risk reduction." (PMID 39315805, 2024). "In cirrhosis, myeloid cell enrichment further drives immune suppression by secreting IL‐10 and TGF‐β, which suppress DC antigen presentation." (PMID 41057994, 2025). "Second, cirrhosis skews macrophages toward high output of immunosuppressive cytokines, include IL-10 and TGF-β, and increased PD-L1 expression, establishing an immune “OFF” configuration." (PMID 41488615, 2025). "It is worth noting that CD169+ monocytes from patients with cirrhosis highly express both IL-10 and IL-6." (PMID 38413535, 2024). "In contrast, CRP, PCT, and the average levels of IL-6 and IL-10 are higher in ACLF than in patients with decompensated cirrhosis." (PMID 39337069, 2024). "The results indicated that IL-6, IL-10 and IL-8 were higher in cirrhosis patients than in healthy controls." (PMID 38413535, 2024). "Persistent alterations are observed only in chronic HCV patients with cirrhosis, displaying a distinct long-term pattern compared to IL-10, IL-22, TNFα, IFNγ, and IL-6." (PMID 39578604, 2024). "In a cohort of 51 patients with a diagnosis of ACLF and decompensated cirrhosis, the degree of SI (levels of IL-10, IL-6, and TNF-α) determines the outcome." (PMID 39337069, 2024). "Insufficient attention has been paid to IL-2 and IL-10 in the field of cirrhosis, which indicate potential avenues for further research." (PMID 37872967, 2023).
Cirrhosis (continued). "This study indicates that IL-10–1082GA + AA and AA genotype carriers are more likely to develop cirrhosis than GG carriers." (PMID 37101651, 2023). "A higher trend of pro-inflammatory cytokines including IL-1α, IL-1β, IL-6, IL-8, IFN-γ and TNF-α was detected in the plasma from ACLF patients than that from cirrhosis patients, as well as the anti-inflammatory cytokines including IL-4, IL-10 and IL-13." (PMID 37380987, 2023). "Cytokine levels of IFN-α2, IFN-γ, TNF-α, IL-6, IL-8, IL-10, IL-17A, IL-18, IL-23, and IL-33 were significantly elevated in patients with decompensated cirrhosis compared to patients with compensated cirrhosis." (PMID 38077228, 2023). "Prior studies have demonstrated increased levels of IL-10 and IL-10 producing T-cells in AH compared to both patients with cirrhosis and healthy controls." (PMID 35286322, 2022). "Growing evidences revealed higher levels of IL6, TNFα, IL1β, and IL10 in HCC patients with cirrhosis compared with those infected with HBV or HCV in the absence of cirrhosis." (PMID 32164265, 2020). "Elevated IL-10 was suggested to mediate disease progress, from inactive state to cirrhosis and HCC in HBV infection." (PMID 33219288, 2020). "In liver diseases (e.g., CHB, cirrhosis and liver cancer), NK cell dysfunction is induced by elevated levels of IL-10 and TGF-β." (PMID 32582704, 2020). "It exerts immunomodulatory effects via maintaining low endotoxin levels and stimulating the production of IL-10 in experimental cirrhosis mice." (PMID 31428083, 2019). "One study that compared cytokine levels in biliary atresia children with advanced cirrhosis with those in healthy children found anti-inflammatory cytokines IL-10 and IL-6 to be elevated." (PMID 30740106, 2019). "This study also suggests an intestinal origin of IL-10 in cirrhosis, a possible adaptive response to enterocyte stress due to portal hypertension." (PMID 28051160, 2017). "Serum IL-10 levels have been reported in patients with chronic hepatitis and cirrhosis and IL-10 can restrain the host’s anti-HBV activity." (PMID 27348302, 2016). "Earlier studies showed increased serum levels of interleukin 6 (IL-6) and interleukin 10 (IL-10) in patients with ACLF compared to those of patients with stable cirrhosis, in a manner similar to that reported in patients with severe sepsis." (PMID 27578545, 2016). "Concomitantly, IL-10 serum concentrations were elevated in patients with cirrhosis showing a trend of a positive linear correlation between serum IL-10 and LBP." (PMID 23446058, 2013). "In this study we found an elevated level of circulating IL-10 in patients with HCV, cirrhosis, and HCC and the concentrations are associated with disease progression." (PMID 27335826, 2013). "IL-10 serum levels in cirrhosis significantly increased from responders through null-responders towards one of the viral antigens to null-responders to both viral antigens (P for trend = 0.003; Jonckheere-Terpstra test)." (PMID 23446058, 2013). "Our results showing a negative association between intrahepatic IL10 mRNA expression and increased ALT, AST and GGT levels with the progression of liver disease to cirrhosis corroborate reports in the literature demonstrating the antifibrotic and antifibrogenic roles of IL-10 in liver damage." (PMID 33125400, 2020). "However, we did not observe a significant correlation of HLA-DR expression on CD14+ monocytes with liver function or stage of cirrhosis or circulating IL-10 levels." (PMID 23446058, 2013). "Moreover, we found heightened level of serum IL-10 in ACLF compared with cirrhosis and HCs." (PMID 36505417, 2022). "This was associated with a significant reduction in tumor necrosis factor receptors 1 and 2 and interleukin-10 (IL-10) concentrations, providing proof of concept evidence that the functional phagocytic defect and the altered cytokine profile observed in cirrhosis could be restored with LcS." (PMID 32498372, 2020).
Cirrhosis (continued). "Regarding IL-10, patients classified as BCLC A presented much higher serum levels of this interleukin when compared to the BCLC B group and the cirrhosis group." (PMID 41379186, 2025). "Next, we detected plasma inflammatory mediators (IL-6, IL-10, TNF-α, IL-8 and IL-12p70) in patients with cirrhosis and controls." (PMID 38413535, 2024). "Here, patients with decompensated cirrhosis had significantly higher serum levels of Int-α2, Int-γ, TNF-α, IL-6, IL-8, IL-10, IL-23, and IL-33 compared to compensated patients, both in blood obtained from hepatic and jugular veins." (PMID 38077228, 2023). "The converse was seen with the anti-inflammatory cytokine, IL-10, which was significantly reduced in the serum at the HCC timepoint compared to inflammation and cirrhosis timepoints (P = 0.022 and P = 0.032, respectively)." (PMID 33858327, 2021). "Compared to healthy controls, patients with cirrhosis had higher circulating levels of LBP and IL-10, an expansion of peripheral blood CD14+ monocytes with low HLA-DR expression and an increased fraction of CD25-positive CD4+ and CD8+ T cells." (PMID 23446058, 2013). "This is fully in agreement with our data, where patients in the BCLC B group had a lower level of this cytokine compared to the other groups and consequently a higher TNF-α/IL-10 ratio of 14.7 versus 2.4 and 3.3 in the BCLC A and cirrhosis groups, respectively." (PMID 41379186, 2025). "Previous research has demonstrated an increase in the number of M1 macrophages in an experimental model of cirrhosis induced by CCl4; in that research, treatment with IFC-305 prevented this increase and favored the production of the anti-inflammatory cytokine IL-10." (PMID 37796781, 2023). "Subgroup analyses for IL-10–1082 GA + AA vs. GG, IL-10–1082 AA vs. GG, and IL-18 -137 GG vs. CC were not conducted for each etiology of cirrhosis reported by only one study." (PMID 37101651, 2023). "Furthermore, the administration of rifaximin for 4–12 weeks has been shown to decrease the blood levels of IL-6, IL-10, and TNF-α in patients with nonalcoholic fatty liver disease and cirrhosis with HE." (PMID 36983211, 2023). "Compared with healthy controls, serum IL-10 was elevated in patients with HCV, cirrhosis, or HCC." (PMID 36117587, 2022). "A corresponding increase in IL-6 and the anti-inflammatory cytokine, IL-10 was induced by NAFLD-HCC BE compared to both NAFLD-cirrhosis and non-NAFLD control BE (P = 0.001 and P = 0.003, respectively)." (PMID 33420074, 2021). "And this is consistent with previous reports that norfloxacin could enhance a regulatory T cell-mediated inflammatory control in cirrhosis by maintaining low IL-2 and IFN-γ levels and stimulating IL-10 production." (PMID 31428083, 2019). "Moreover, Guo and colleagues found that the IL‐10 GCC haplotype (rs1800896, rs1800871, rs1800872) likely reduced the risk of cirrhosis in HBV‐HCV patients, despite no distinct association observed for these three SNPs in either the general or Asian population." (PMID 39315805, 2024). "However, our study did not observe a correlation between IL‐10‐592 and the progression of cirrhosis in patients with chronic HBV infection or any synergistic effect between IL‐10‐592 and IL‐10‐1082." (PMID 39315805, 2024).
heart failure (62 papers, 2009 to 2026). Inability of the heart to pump blood at an adequate rate to meet tissue metabolic requirements. "In a heart failure with preserved ejection fraction (HFpEF) model, NETs were associated with macrophage infiltration and inflammatory responses; the breakdown of NETs by DNase 1 significantly reduced macrophage numbers in cardiac tissue and decreased IL-10 expression in macrophage." (PMID 40109341, 2025). "Reduced IL-10 levels impair the effective suppression of pro-inflammatory cytokine release, leading to uncontrolled inflammation, which is closely associated with complications like respiratory failure and heart failure frequently observed in moderate-to-severe cases." (PMID 41425878, 2025). "Compared with heart failure-associated transudative ascites, malignant ascites demonstrated higher levels of TNF-α, IL-6, IL-10, IL-12p70, IL-18, IL-23, s4-1BB, and TGF-β1, while albumin levels were lower." (PMID 42193466, 2026). "The results showed that the expression levels of HIF-1α, IL10, PAD4, ACTG1, SOD2, and GAPDH were higher in heart failure patients with Qi deficiency and blood stasis syndrome compared to the HP group." (PMID 40671145, 2025). "Reports suggest that exercise can stimulate macrophages in heart failure mice to secrete IL‐10, promote p‐STAT3/S100A9 nuclear translocation, and regulate the differentiation of myeloid‐derived suppressor cells, thus achieving cardioprotection." (PMID 38504474, 2024). "Colchicine can be used to boost IL-10 levels with anti-inflammatory protection, specifically in the context of managing inflammation and preventing heart failure." (PMID 39200761, 2024). "In all CHF patients, higher TNF, IL-10, SOCS1 and SOCS3 gene expression was associated with severity of heart failure according to MR-proANP (r = 0.4, p < 0.03, r = 0.39, p < 0.03, r = 0.45, p < 0.03 and r = 0.45, p < 0.02, respectively)." (PMID 38337428, 2024). "Circulating levels of cytokines: IL-1β, TNFα, IL-10, IL6, IL-8 and IL-12 were determined and investigated regarding their association with hemodynamic parameters, clinical signs of heart failure and outcome." (PMID 36014020, 2022). "The gene transfer of human interleukin-10 (a potent anti-inflammatory) using intraventricular administration in a rat model of heart failure resulted in amelioration of heart failure symptoms." (PMID 35309046, 2022). "In rats with heart failure following MI, IL-10 therapy significantly improved post-MI left ventricular function." (PMID 36140236, 2022). "In rats with heart failure, IL-10 therapy significantly improved post-MI left ventricular function by reducing IL-6 and TNF-α, whilst in ischemia-reperfusion injury, IL-10 therapy reduced inflammation and cardiomyocyte death." (PMID 36140236, 2022). "In patient with heart failure, both the percentage of human leukocyte MDSCs in the blood and plasma level of IL-6, IL-10 were significantly increased." (PMID 36263056, 2022). "Previously, high levels of IL-10 have been found in heart failure after acute myocardial infarction." (PMID 33122738, 2020). "The obtained results have proven that our MNPs can represent a promising tool for rapid pre-concentration of heart failure biomarkers (TNF-α/IL-10) in saliva." (PMID 32878151, 2020). "Our findings indicate overexpression of Klotho in macrophages can restore IL-10 expression and promote macrophage M2 polarization in kidney and heart tissue to alleviate IS-induced heart failure and kidney damage." (PMID 32464602, 2020). "So far, it has been found that inflammatory cytokines associated with the heart failure mechanism include TNF-α, IL-6, IL-8, IL-10, IL-1α, IL-1β, IL-2, TGF-β, and IFN-γ." (PMID 31275453, 2019). "Circulating IL-10 levels were diminished in patients with heart failure, while it has been reported that elevated levels of IL-10 and TNF-α was associated with an increased risk of mortality." (PMID 30177883, 2018).